SOST (sclerostin)
Diseases named in the same sentence as SOST in open-access papers (continued):
Sharing a sentence is not in itself a finding about the gene and the disease.
Insulin resistance (continued). "The aim of this study was to evaluate the circulating sclerostin levels to nutritional status, insulin resistance and hormonal disturbances in women with PCOS." (PMID 32592042, 2020). "Pre-clinical observations were confirmed by clinical studies showing that sclerostin levels are higher in pre-diabetes subjects than in controls, and correlate with insulin resistance." (PMID 32265831, 2020). "An analysis performed in groups with and without insulin resistance (HOMA-IR ≥ 2 vs. < 2) showed that plasma sclerostin levels were significantly higher in the group with insulin resistance." (PMID 32592042, 2020). "These authors suggested that sclerostin plays an important role in the regulation of glucose metabolism regardless of other fat and bone-derived factors and decreased insulin resistance." (PMID 32592042, 2020). "Sclerostin was positively correlated with HbA1c and may induce insulin resistance via endoplasmic reticulum stress." (PMID 40149867, 2025). "Additionally, a Polish study involving 55 obese children and adolescents with a mean age of 13.2 ± 3.4 years, and 26 sex- and Tanner stage-matched healthy controls, examined the relationship between serum sclerostin levels and insulin resistance." (PMID 40353858, 2025). "Lastly, whether metabolic actions of sclerostin (fat metabolism, insulin resistance etc.)impacts graft function and cardiovascular events needs further assessment." (PMID 39078512, 2024). "Another study demonstrated that serum sclerostin levels were associated with insulin resistance and nutritional status but not with sex hormone disorders in women with PCOS." (PMID 38111425, 2023). "While SIRT1 decreases with increasing body fat, sclerostin expression increases in parallel with adipose tissue and insulin resistance, and promotes adipocyte hypertrophy and the differentiation of bone precursors into white adipocytes, reducing bone formation." (PMID 35267956, 2022). "Sclerostin levels are strongly correlated with plasma insulin and insulin resistance." (PMID 35742035, 2022). "Besides, higher sclerostin levels were found in subjects with prediabetes, as well as with type 1 and 2 diabetes, and a positive correlation between sclerostin levels and insulin resistance was showed." (PMID 32592042, 2020). "The researchers concluded that sclerostin may play a significant role in regulating glucose metabolism in children and adolescents, independent of other fat- and bone-derived factors, and that in obese youth, it may contribute to reducing insulin resistance." (PMID 40353858, 2025). "In T2D, sclerostin, a product of the osteocytes which impairs bone formation and stimulate bone resorption, is increased, however, it is unknown whether osteocytes are influenced by insulin resistance." (PMID 35360074, 2022). "The reasons for different correlations being found between fasting insulin or HOMA-–IR and serum sclerostin may be related to differences in study population and/or issues with the validity of surrogate markers for insulin resistance in children and adolescents." (PMID 34572220, 2021). "Indeed, sclerostin has been reported to positively affect glucose metabolic control in patients with T1DM, and a negative association with insulin resistance and sclerostin levels in obese subjects has been found." (PMID 33801212, 2021). "Obese subjects with insulin resistance (higher HOMA-IR and lower oral glucose insulin sensitivity index) had higher expressions of DKK1, DKK2, sclerostin, and sFRP-1 but lower expression of osteogenic microRNA and β-catenin." (PMID 37569816, 2023). "Serum/plasma concentrations of glucose, insulin (with the calculation of homeostatic model assessment insulin resistance—HOMA-IR), estradiol, total testosterone, sex hormone-binding globulin (SHBG) and sclerostin were measured." (PMID 32592042, 2020).
Insulin resistance (continued). "Obese individuals with insulin resistance presented significantly higher sclerostin mRNA expression in blood compared with those without insulin resistance." (PMID 40149867, 2025). "None of the clinical trials evaluating therapeutic sclerostin-neutralizing antibodies (Scl Ab) to date report fat mass or insulin resistance as outcomes." (PMID 33776907, 2021). "Clinical data showed negative correlations between sclerostin, insulin, and homeostasis model assessment of insulin resistance (HOMA-IR) in 55 children and adolescents with simple obesity." (PMID 32265831, 2020). "Notwithstanding a study performed among children showed a negative correlation between sclerostin levels and insulin resistance." (PMID 32592042, 2020). "Circulating sclerostin levels in women with PCOS is related to nutritional status and insulin resistance, but not to sex hormone disturbances." (PMID 32592042, 2020). "Circulating sclerostin levels in women with PCOS are related to nutritional status and insulin resistance, but not to sex hormone disturbances." (PMID 32592042, 2020).
Osteopenia (28 papers, 2010 to 2025). Osteopenia is a term to define bone density that is not normal but also not as low as osteoporosis. "Conversely, animal studies have demonstrated enhanced bone formation, mass, and strength in SOST-null mice, while overexpression of the SOST gene results in osteopenia." (PMID 40027001, 2025). "Interestingly, in SM patients, the evidence of high serum levels of sclerostin, a regulator of late osteoblast/pre-osteocyte differentiation associated with osteopenia, and 25(OH)D blood values were negatively correlated, and this might suggest that 25(OH)D influences sclerostin levels." (PMID 34445560, 2021). "Animal studies confirmed that sclerostin knockout mice displayed a high bone mass phenotype with increased bone formation and bone mineral density, while overexpression of sclerostin in mice resulted in osteopenia." (PMID 34361085, 2021). "To date, commercially available antibodies against sclerostin exist, being used to increase bone mass in postmenopausal osteopenia." (PMID 32424558, 2020). "Our assumption is in line with previous in vivo studies, showing that oral annatto TT supplementation prevented osteopenia induced by metabolic syndrome by reducing SOST and DKK1 levels, considered antagonist of the Wnt signalling pathway." (PMID 32629979, 2020). "Second, anti-sclerostin antibody treatment rescued the trabecular osteopenia present in HDAC5−/− animals, which have high levels of SOST expression." (PMID 27759007, 2016). "It was hypothesized that the partial inactivation of sclerostin function by genetic manipulation will rescue the osteopenia induced by high endogenous glucocorticoid levels." (PMID 30664862, 2019). "Mechanistically, sclerostin inhibition in exercised Gfra2−/− mice normalized BFR, strength, and trabecular thickness, highlighting the relevance of sclerostin in the osteopenia of Gfra2−/− mice." (PMID 35276096, 2022). "In Sost−/− mice, Wnt signaling and bone mass was increased, whereas transgenic mice over-expressing Sost in bone tissue had osteopenia, indicating that Sclerostin is an important negative regulator of bone formation." (PMID 23472141, 2013). "Sclerostin appears to be vital for the bone to be able to respond to mechanical loading, and lack of sclerostin prevents osteopenia due to unloading." (PMID 22103277, 2011). "In addition, antihormonal treatment-induced osteopenia may also have a significant impact on DKK-1 and sclerostin levels." (PMID 30116403, 2018).
rheumatoid arthritis (26 papers, 2013 to 2025). A chronic, systemic autoimmune disorder characterized by inflammation in the synovial membranes and articular surfaces. "Rheumatoid arthritis is characterized by decreased bone mass, bone and cartilage erosions, and systemic inflammation and is associated with increased serum sclerostin levels and reduced Wnt signaling." (PMID 35160258, 2022). "Sclerostin has been proposed as an inflammatory regulator based on the experimental findings that sclerostin inhibition can prevent bone loss in patients with rheumatoid arthritis and colitis." (PMID 35562828, 2022). "In addition to this, several studies reported that the effects of sclerostin antibodies on bone loss were associated with inflammatory bone diseases such as rheumatoid arthritis." (PMID 35563281, 2022). "In rheumatoid arthritis (RA), an inflammatory disease of the joints in which bone loss is observed, SOST inhibition promotes TNFα-mediated tissue damage, demonstrating a possible protective role of SOST in TNFα-mediated chronic inflammation." (PMID 34502021, 2021). "The aim of this study was to analyze relationships between receptor activator of nuclear factor kappa-B (RANKL), sclerostin and their gene polymorphisms with radiological progression in patients with early rheumatoid arthritis (RA)." (PMID 28190118, 2017). "In contrast, sclerostin levels decrease in human BMSCs when stimulated with glucocorticoids and in patients with rheumatoid arthritis and polymyalgia rheumatica who necessitate glucocorticoid therapy." (PMID 38679740, 2024). "It has been suggested that in rheumatoid arthritis fibroblast-like synoviocytes were a major source of sclerostin." (PMID 36407318, 2022). "In rheumatoid arthritis, sclerostin was isolated from the synovial tissue, and it is secreted by fibroblast-like synoviocytes and from osteoblasts." (PMID 35160258, 2022). "In contrast to rheumatoid arthritis, sclerostin expression in ankylosing spondylitis is markedly reduced." (PMID 35160258, 2022). "Sclerostin’s role in rheumatoid arthritis is unclear, as there are contradictory findings from animal studies in the literature." (PMID 35160258, 2022). "In rheumatoid arthritis, a systemic inflammatory disease, elevated levels of inflammatory cytokines enhance IL-1β, TNFα, sclerostin (SOST), and DKK1 gene expression in osteocytes." (PMID 32733380, 2020). "In the article titled “Serum Sclerostin Levels in Patients with Ankylosing Spondylitis and Rheumatoid Arthritis: A Systematic Review and Meta-Analysis”, the affiliation listed for the first author was incorrect." (PMID 29181394, 2017). "In a murine model of rheumatoid arthritis, treatment for 21 days with an antibody to sclerostin reversed a decline in several axial and appendicular bone microstructural properties associated with chronic inflammation." (PMID 24432364, 2013). "Additionally, patients undergoing glucocorticoid therapy for conditions such as rheumatoid arthritis, polymyalgia rheumatica and chronic inflammatory diseases exhibited a noteworthy decrease in sclerostin levels." (PMID 38679740, 2024). "Thus, in addition to the inhibitor of Wnt/β-catenin signals, sclerostin may have a role in the suppression of TNF-induced inflammation in rheumatoid arthritis." (PMID 35563281, 2022). "However, sclerostin antibody treatment may promote TNF-dependent inflammatory joint destruction in rheumatoid arthritis patients." (PMID 32708317, 2020). "Under inflammatory conditions like rheumatoid arthritis (RA), FLSs have been shown to possess the ability to secrete WNT antagonists such as DKK1 and SOST." (PMID 34250013, 2021). "Human osteocyte-enriched cells were cultured with serum of active rheumatoid arthritis patients ex vivo, which increased IL-1β, TNF-α, SOST, and DKK1 gene expression levels." (PMID 32708317, 2020).
rheumatoid arthritis (continued). "Expression of sclerostin and DKK1 was elevated in synovial tissue from rheumatoid arthritis patients compared to controls and bone repair was often delayed or repressed in patients with systemic inflammatory background." (PMID 24618907, 2014). "In other studies, elevated levels of the WNT pathway antagonists sclerostin and DKK1 were reported in animal models of rheumatoid arthritis." (PMID 24618907, 2014). "However, In pathological conditions such as rheumatoid arthritis, activated B cells can secrete pro-inflammatory factors, including TNF-α and CCL3, as well as inhibitory molecules like sclerostin (SOST) and Wnt signaling pathway inhibitor 1 (DKK1)." (PMID 41230503, 2025). "In support of this notion, it has been suggested that bone formation is often repressed in patients suffering from rheumatoid arthritis and that DKK1 and sclerostin (inhibitors of bone formation) were detected in serum of these patients and other inflammatory conditions." (PMID 24618907, 2014). "Sclerostin blockade prevented or reversed the decrease in axial and appendicular bone mass in the murine model of rheumatoid arthritis, but did not affect systemic inflammation and was unable to prevent or repair local focal erosion." (PMID 24432364, 2013). "On the contrary, in TNFα-induced rheumatoid arthritis mice that do not express sclerostin (SOST knock-out mice or after antisclerostin antibody administration), a rapid deterioration of rheumatoid arthritis occurred, suggesting that sclerostin may have a protective role." (PMID 35160258, 2022).
osteoarthritis (25 papers, 2013 to 2026). A noninflammatory degenerative joint disease occurring chiefly in older persons, characterized by degeneration of the articular cartilage, hypertrophy of bone at the margins and changes in the synovial membrane. "SOST can regulate the progression of osteoarthritis in bone and cartilage, promote subchondral bone sclerosis, and inhibit cartilage degeneration." (PMID 40563496, 2025). "Patients with osteoarthritis have significantly lower levels of serum sclerostin than healthy controls, and a decrease of osteocyte sclerostin leads to increased bone formation, which explains the protective effect of osteoarthritis to hip fractures." (PMID 35160258, 2022). "A knee anterior cruciate ligament transection (ACLT) mouse osteoarthritis (OA) model on SOST-knockout (SOST KO) and wild-type (WT) mice was established." (PMID 31828128, 2019). "Our research describes for the first time the perioperative changes observed in serum DKK1 and SOST levels of osteoarthritis (OA) patients undergoing TJA." (PMID 28953627, 2017). "Because bone tissue contributes to the development of osteoarthritis (OA), we investigated the role of sclerostin in bone and cartilage in a joint instability model in mice." (PMID 25656376, 2015). "Although additional research is needed to sustain such a claim, recent evidence demonstrated that the addition of WNT and BMP antagonist sclerostin was able to prevent an IL-1β-induced osteoarthritis-like phenotype." (PMID 24286177, 2013). "The degree of osteoarthritis can affect the sclerostin levels." (PMID 35742035, 2022). "Low sclerostin levels in aging mice, or the administration of the antisclerostin antibody in rats with surgically induced osteoarthritis did not cause any further damage in articular cartilage, despite the Wnt-signaling upregulation." (PMID 35160258, 2022). "Interestingly, sclerotic subchondral bone in osteoarthritis exhibits decreased sclerostin expression, possibly because of increased mechanical forces." (PMID 35160258, 2022). "Given that upregulation of the canonical Wnt-signaling pathway in chondrocytes deteriorates osteoarthritis, sclerostin expression may have a protective role." (PMID 35160258, 2022). "Early stages of osteoarthritis increase sclerostin-positive osteocytes in the subchondral bone." (PMID 35742035, 2022). "In contrast, SOST knock-out mice developed severe osteoarthritic changes after medial meniscus destabilization but with no osteophyte formation, suggesting a possible protective role of sclerostin in osteoarthritis." (PMID 35160258, 2022). "Because astronauts experience an increased incidence of post-traumatic osteoarthritis involving their knees, ankles, hips, and shoulders, their use of anti-sclerostin antibody during spaceflight may prove to be a double-edge sword." (PMID 32947946, 2020). "Hence, sclerostin should be further evaluated as a pharmaceutical target for osteoarthritis treatment in the case of abnormal loading patterns experienced by patients on long-term bed rest or astronauts on long-term space missions." (PMID 31584963, 2019). "In addition, the recent findings of sclerostin expression in chondrocytes shed light on the potential contribution to the pathogenesis of cartilage diseases, including osteoarthritis (OA)." (PMID 30071108, 2018). "This conflicting response to the cartilage breakdown between SOST knock-out mice and the antisclerostin-antibody treatment is probably due to insufficient diffusion of sclerostin in articular cartilage and implies that an additional trigger is required to initiate osteoarthritis." (PMID 35160258, 2022). "However, in advanced osteoarthritis, the number of sclerostin-positive osteocytes decreases." (PMID 35742035, 2022).
osteoarthritis (continued). "As E11 is essential for the formation of osteocyte dendrites, we therefore hypothesised that the ablation of E11 from bone cells would lead to SCB thickening and exacerbated osteoarthritis pathology via a decreased osteocyte production of the bone formation inhibitor, sclerostin." (PMID 31351471, 2019). "Sclerostin is a small protein expressed by chondrocytes and osteocytes; it is not completely understood how reduced levels of sclerostin contribute to osteoarthritis but it is hypothesized that sclerostin prevents Wnt-pathway modulated expression of disintegrin and metalloproteinase." (PMID 30460596, 2018). "In addition, there is evidence in experimental animals that sclerostin generated in response to TNF-α and IL-1β improves post-traumatic osteoarthritis by inhibiting the activity of proteolytic enzymes involved in cartilage degradation." (PMID 32947946, 2020). "Immunohistochemical and qRT-PCR analysis of β-catenin, TCF-4, and SOST/Wise revealed an elevated expression of β-catenin and TCF-4 in the intermediate and late stages of osteoarthritis, whereas sclerostin levels were lower compared to levels in the early-stage osteoarthritis samples." (PMID 31546898, 2019). "Sclerostin (SOST), a soluble antagonist of Wnt signaling, is expressed in chondrocytes and contributes to chondrocytes’ hypertrophic differentiation; however its role in osteoarthritis (OA) pathogenesis is not well known." (PMID 26071314, 2015).